AR (androgen receptor)
Diseases named in the same sentence as AR in open-access papers (continued):
Sharing a sentence is not in itself a finding about the gene and the disease.
neutropenia (5 papers, 2020 to 2022). A decrease in the number of neutrophils found in the blood. "Previous studies have shown that the androgen receptor is important for the development of neutrophils, as AR-deficient mice have been shown to suffer from neutropenia due to reduced proliferative activity of neutrophil precursor cells." (PMID 32235862, 2020). "Previously, AR deficient mice were shown to suffer from neutropenia due to reduced proliferative activity of neutrophil precursor cells." (PMID 32235862, 2020). "Neutropenia as one of the major side effects of chemotherapy leading to impaired immune response and availability of modern androgen receptor targeted agents might be factors leading to this decision." (PMID 32623500, 2021). "It has been shown that the lack of androgen receptor (AR) causes neutropenia and increases the susceptibility to microbial infection." (PMID 32714332, 2020).
papillary thyroid cancer (5 papers, 2015 to 2024). "In addition, the pattern of low AR expression was associated with high cancer risk and extrathyroidal extension during the tumor progression in papillary thyroid carcinoma." (PMID 32365531, 2020). "More recently, a 2.7-fold reduction in androgen receptor expression was detected in papillary thyroid cancer versus matched normal tissue." (PMID 37635968, 2023). "Testosterone increased dose-dependent proliferation of AR+ human papillary thyroid cancer cell lines; whereas flutamide, inhibited testosterone-induced cell proliferation [S13]." (PMID 25595907, 2015). "Using RNA-sequencing, we profiled the immune landscape of papillary thyroid cancer (PTC) and identified a significant inverse correlation between androgen receptor (AR) levels and the immune checkpoint molecule PD-L1." (PMID 34422798, 2021).
premature ovarian failure (5 papers, 2009 to 2024). "Studies employing global AR knockout (ARKO) female mice, according to well-defined roles of AR in male reproduction, indicate that these subjects are subfertile, have defective folliculogenesis, and ultimately develop premature ovarian failure." (PMID 29546053, 2018). "Inactivation of AR in female mice results in premature ovarian failure, indicating that normal folliculogenesis requires AR-mediated androgen action." (PMID 19589134, 2009).
renal fibrosis (5 papers, 2021 to 2025). A final common manifestation of a wide variety of chronic kidney diseases characterized by glomerulosclerosis and tubulointerstitial fibrosis. "Treatment of male rats with flutamide, an AR antagonist, has been reported to systematically downregulate cytokines in renal fibrosis, while an increased AR expression was observed in mice during severe infection with HBV." (PMID 40406098, 2025). "As the transcription of Fgf10 and Fgfr2 depends on AR signaling, exposure to DBP disrupted the Fgf10/Fgfr2 signaling pathway in the kidneys, this being a crucial factor in the development of renal fibrosis." (PMID 39728417, 2024).
rheumatoid arthritis (5 papers, 2014 to 2022). A chronic, systemic autoimmune disorder characterized by inflammation in the synovial membranes and articular surfaces. "For example, shorter polyQ1 is associated with increased activity of AR, which can cause PCa and rheumatoid arthritis." (PMID 36388907, 2022).
skin cancer (5 papers, 2013 to 2025). "In support of a role for stromal AR in cancer aggressiveness, it has been shown that AR targeting in CAFs reduces skin cancer aggressiveness traits or even inhibit the development of chemo-resistant skin cancers." (PMID 35222290, 2022).
uterine cancer (5 papers, 2019 to 2024). Primary or metastatic malignant neoplasm involving the uterine corpus and/or the cervix. "Until now, the molecular biological mechanism of the androgen/AR system for the development and progression of uterine cancer has remained unclear." (PMID 38890503, 2024). "Although details of the effects of male hormones on the uterus are still unknown, the possible involvement of androgen in the development of uterine cancer has been proposed since the androgen receptor (AR) is expressed in endometrioid carcinoma." (PMID 38890503, 2024). "Since some cases of uterine cancer and Luminal A breast cancer with good survival share high CNV load, low immune infiltration, and high AR, PR and ER α protein expression, Luminal A therapies could work for uterine cancer cases with such characteristics." (PMID 31671657, 2019).
-dependent (4 papers, 2013 to 2021). "It has been confirmed that CRPC is still an androgen-dependent disease that relies on androgen receptor (AR) signaling." (PMID 33441906, 2021). "It is an androgen-dependent disease whose growth and progression depends on the transcriptional activity of the androgen receptor (AR), also a master regulator of normal prostate epithelial cell differentiation." (PMID 32019175, 2020). "Collectively, these data indicate that miR-19a, miR-27a and miR-133b are the truly direct targets of AR in androgen-dependent PCa with up-regulated expressions." (PMID 23451058, 2013). "It is initially an androgen-dependent disease that may progress to an androgen-independent stage: castration resistant prostate cancer (CRPC) with poor prognosis related to the reactivation of androgen-receptor (AR) transcriptional activity." (PMID 30959962, 2019).
acute promyelocytic leukemia (4 papers, 2012 to 2020). An aggressive form of acute myeloid leukemia (AML), characterized by arrest of leukocyte differentiation at the promyelocyte stage, due to a specific chromosomal translocation t(15;17) in myeloid cells. "The main isoform of ZNF451 is a nuclear protein that, upon sumoylation, localizes to promyelocytic leukemia bodies and interacts with the androgen receptor." (PMID 25735770, 2015).
anemia (4 papers, 2022 to 2025). A reduction in the number of red blood cells, the amount of hemoglobin, and/or the volume of packed red blood cells. "Among the variables analyzed, AR alterations emerged as an independent predictor for PFS (p = 0.0022), alongside anemia, while site score, PSA, and LDH were not statistically significant." (PMID 40558023, 2025).
atrial fibrillation (4 papers, 2012 to 2025). A disorder characterized by an electrocardiographic finding of a supraventricular arrhythmia characterized by the replacement of consistent P waves by rapid oscillations or fibrillatory waves that vary in size, shape and timing and are accompanied by an irregular ventricular response. "In atrial fibrillation, single-nucleus multi-omics implicated androgen-receptor signaling in cardiomyocytes and NR4A1 regulation in fibroblasts, suggesting hormonal modulators as potential interventions in atrial cardiomyopathy." (PMID 41393100, 2025). "Future studies should determine whether the increase in A2a-AR is the cause or the result of atrial fibrillation in humans." (PMID 33574762, 2020).
autoimmune myocarditis (4 papers, 2019 to 2025). Autoimmune myocarditis is an autoimmune disease that affects the heart. "Androgen receptor (AR) inhibition alleviates inflammation in experimental autoimmune myocarditis by enhancing autophagy, especially in macrophages." (PMID 40968543, 2025). "Androgen receptor (AR) inhibition exerts anti‐inflammatory effects to promote tissue repair in an experimental autoimmune myocarditis (EAM) mouse model." (PMID 37434325, 2024). "In our previous study, we proved that suppressed androgen receptor (AR) alleviated inflammation during experimental autoimmune myocarditis (EAM)." (PMID 30956636, 2019). "Similarly, miR-125b was found to enhance fibrogenic pathways in mice with experimental autoimmune myocarditis because of an overexpression of the androgen receptor (AR)." (PMID 31671621, 2019).
Cachexia (4 papers, 2013 to 2020). Severe weight loss, wasting of muscle, loss of appetite, and general debility related to a chronic disease. "Another potential reason for exogenous androgens’ failure is a cachexia‐mediated global disruption of AR signaling." (PMID 31930715, 2020). "Comparable trials testing the effect of novel anti-cachexia drugs [e.g., anamorelin or selective androgen receptor modulators (SARMs)] have used body composition measurement such as lean body mass (total or appendicular) as outcome measure." (PMID 33585533, 2020). "Skeletal muscle and testes androgen receptor expression were decreased with severe cachexia." (PMID 24285707, 2013).
cardiomyopathy (4 papers, 2017 to 2024). A disease of the heart muscle or myocardium proper. "In fact, mutant AR-driven cardiomyopathy is the most likely explanation for the sudden and unexpected demise of aged BAC fxAR121; HSA-Cre mice." (PMID 37269008, 2023).
clear cell carcinomas (4 papers, 2016 to 2025). "Within the subtypes of HGEC, the most pronounced loss of AR was observed in the clear-cell carcinoma group (P=0.001); albeit ERα expression scores in the same group remained moderate to strong." (PMID 26930451, 2016). "Although we found frequent AR overexpression in clear cell carcinomas without the ARv7 splice variant, potential therapeutic benefit of anti‐AR–based therapy alone in clear cell carcinomas expressing ER is uncertain." (PMID 32279409, 2020). "In addition, two of three clear cell carcinomas with PI3K/PTEN alterations were AR+." (PMID 32279409, 2020). "Finally, one of the most notable findings is seen in the clear cell carcinoma (CCCA) category, in which AR is the solely expressed receptor." (PMID 40392873, 2025). "For example, AR has been expressed in 50% of clear cell carcinomas with no co-expression of either ER or PR." (PMID 37725629, 2023). "Also, our findings confirm the results of the recent studies that found a significant expression of AR in high-grade serous and clear cell carcinomas in the absence of ER and PR positivity." (PMID 37725629, 2023).
coronary artery disease (4 papers, 2016 to 2024). "Potentially the exclusion of patients with existing coronary artery disease may have resulted in an underestimation of any association between AR expression and calcification in this study." (PMID 27095121, 2016). "AR signaling pathway also plays a role in coronary heart disease." (PMID 39470548, 2024).
endometrial tumor (4 papers, 2016 to 2024). "The loss of estrogen, progesterone, and androgen receptor expression has been used to define clinically-relevant subtypes of endometrial tumors that are associated with poor outcomes." (PMID 32894083, 2020). "This highlights intra-tumoral 11-oxyandrogen metabolism as an important source of AR-activating hormones in endometrial tumors." (PMID 39205690, 2024). "In mouse models of type I EC, short-term enzalutamide treatment, an inhibitor of AR signaling, reduced endometrial tumor burden and increased cancer cell apoptosis in a dose-dependent way." (PMID 35814433, 2022). "We next wondered whether endometrial tumors could metabolize 11-oxyandrogen precursors, including 11βOHA4 and 11KA4 to AR-activating 11-oxyandrogens, such as 11KT and 11KDHT." (PMID 39205690, 2024).
esophageal adenocarcinoma (4 papers, 2010 to 2023). A malignant tumor with glandular differentiation arising predominantly from Barrett mucosa in the lower third of the esophagus. "Relevant study reported androgen receptor regulated the growth of esophageal adenocarcinoma in a paracrine manner." (PMID 33823125, 2021). "The expression of the androgen receptor (AR) in OC is noteworthy, as studies have indicated a reduction in the occurrence of esophageal squamous carcinoma (ESCC) and esophageal adenocarcinoma (EAC) subsequent to androgen deprivation therapy." (PMID 38288469, 2023).
glaucoma (4 papers, 2009 to 2025). Increased pressure in the eyeball due to obstruction of the outflow of aqueous humor. "The father's family had a history of glaucoma, ruling out the causative effect of the receptor gene in the pathogenesis of glaucoma and exon 6 of the androgen receptor gene of the mother was normal; therefore, the mutation was considered de novo." (PMID 26451378, 2015). "Consistent with our results, animal models of glaucoma showed robust activation of pathways mediated by AP-1/c-Fos/c-Jun, NF-κB, complement, androgen receptor and ephrins." (PMID 19426536, 2009). "Additionally, elevated levels of AR have been detected in glaucomatous astrocytes, suggesting a potential role of androgen metabolism in contributing to optic nerve damage in glaucoma." (PMID 40647681, 2025).
Glucose intolerance (4 papers, 2009 to 2024). Glucose intolerance (GI) can be defined as dysglycemia that comprises both prediabetes and diabetes. "Conversely, the selective knockout of the AR in mice β-cells was associated with glucose intolerance due to a reduction in glucose-stimulated insulin secretion, leading to hypoinsulinemia, glucose intolerance, and hyperglycemia." (PMID 31817436, 2019). "While one would expect differing phenotypes, increases in weight gain and adiposity, glucose intolerance, and insulin insensitivity, are observed in both AR deficient and ERα deficient mice." (PMID 19789640, 2009).
Hypercholesterolemia (4 papers, 2015 to 2023). An increased concentration of cholesterol in the blood. "In addition, hypercholesterolemia is associated with elevated androgen levels as well as the androgen receptor (AR)." (PMID 37312170, 2023). "Previously, in tumor xenografts (PC-3 cells) from an animal model of CRPC with diet-induced hypercholesterolemia, we demonstrated that cholesterol could trigger the translocation of these proteins, upregulate their expression and increase AR expression, which was associated with tumor progression." (PMID 37298588, 2023). "In conjunction with restoring miR-137 expression, hypercholesterolemia may contribute to miR-137/coactivators p160/AR axis homeostasis." (PMID 37298588, 2023). "While PC-3 cells lack androgen receptor expression, it was possible that hypercholesterolemia increased circulating testosterone levels which could positively affect tumor stroma tissues." (PMID 25924234, 2015). "We show that diet-induced hypercholesterolemia accelerated secondary tumor metastases to lymph node, lung and bones in orthotopic xenograft mice using androgen receptor negative PC-3 cells." (PMID 25924234, 2015).
hyperplasia (4 papers, 2016 to 2025). An abnormal increase in the number of cells in an organ or a tissue with consequent enlargement. "The present study showed, for the first time to our knowledge, antiproliferative effects of paddy waste product on rat prostate hyperplasia growth through AR downregulation in a SHR model." (PMID 40115867, 2025). "A cohort of 13 TSPs, 6 EPTs, 17 ABCs, and 8 adenoid basal hyperplasia (ABH) was analyzed for expression of prostatic markers HoxB13, NKX3.1, p16, and androgen receptor (AR)." (PMID 41335140, 2025).
intraepithelial neoplasia (4 papers, 2014 to 2025). A precancerous neoplastic process that affects the squamous, glandular, or transitional cell epithelium without evidence of invasion. "Loss of AR expression was reported to be a common event in intraepithelial neoplasia and invasive squamous cell carcinoma associated with high-risk HPV infection of the cervix." (PMID 31892232, 2019). "Moreover, the increased androgen receptor (AR) activity is present in cases of intraepithelial neoplasia and PC." (PMID 25309637, 2014). "Here, we report that HFD modified the final body weight and the weight gain, decreased the expression of the androgen receptor and increased prostatic inflammation via TNF-α produced damage prostatic like intraepithelial neoplasia." (PMID 33737530, 2021). "While AR expression increased in conjunction with cytologic atypia and HER2 expression was reserved for overt epithelial dysplasia, these markers also did not impact prognosis." (PMID 40938457, 2025).
invasive lobular carcinoma (4 papers, 2019 to 2025). "Our results showed that invasive lobular carcinoma represented a TNBC morphologic variant with higher lymph node ratio (> 0.65), higher AR expression and lower TILs component, than those of other histologic special types." (PMID 32487046, 2020).
ischemic stroke (4 papers, 2022 to 2025). A stroke disorder caused by obstruction of blood flow to the brain, due to thrombotic (local blood clot formation) or embolic (due to a blood clot or other material traveling from another site) event. "The small sample size of this study imposes a limit on the further analysis of the influence of different AR blockers on the systemic immune response and outcomes of patients with ischemic stroke." (PMID 36778208, 2023). "AR expression was reduced after cerebral ischemia, and overexpression of AR reduced the infarct size after ischemic stroke." (PMID 36569944, 2022).
liver cirrhosis (4 papers, 2013 to 2022). "Accordingly, in the present study, it was evaluated the ability to reverse liver cirrhosis by treatment with doxazosin and carvedilol, as well as the cotreatment with curcumin, looking to attenuate the toxic effects of these AR blockers." (PMID 31183386, 2019). "In mouse models of liver cirrhosis induced by either CCl4 or thioacetamide treatment, the knock-down of the androgen receptor improved migration as well as anti-inflammatory and anti-fibrotic actions thus augmenting liver repair." (PMID 24758938, 2014).
mantle cell lymphoma (4 papers, 2017 to 2024). Mantle cell lymphoma is a rare form of malignant non-Hodgkin lymphoma affecting B lymphocytes in the lymph nodes in a region called the ``mantle zone''. "While it is not clear what underlies the poor outcomes in men with mantle cell lymphoma, AR is expressed across an array of hematopoietic cells, and may account for gender differences in the function of platelets and the immune system." (PMID 28085048, 2017).
medulloblastoma (4 papers, 2012 to 2024). A malignant, invasive embryonal neoplasm arising from the cerebellum. "From the compendium of cell lines that have been processed for DNase-seq through the ENCODE project, we identified H1 embryonic stem cells and D721 medulloblastoma cells as having relatively low expression levels of the AR." (PMID 23034120, 2012). "AGL was the only AR gene that had P/LP variants enriched in cases compared to controls (p=0.035) and has not been previously associated with medulloblastoma." (PMID 39184053, 2024).
memory impairment (4 papers, 2016 to 2025). "The present study used AR-deficient Tfm male mice with learning and memory impairments to study the effects of androgens mediated by ZIP9 on hippocampal learning and memory." (PMID 37305050, 2023). "To summarize, it can be concluded that gonadectomy (GDX-vehicle group) caused memory impairments and it can decrease the density of androgen receptor-ir neurons in CA1, CA3, DG areas of the hippocampus." (PMID 26822779, 2016). "In the present study, the role of gonadectomy on memory impairment and the density of androgen receptor-immunoreactive neurons in rats’ hippocampus as well as the ability of testosterone to compensate of memory and the density of androgen receptors in the hippocampus was evaluated." (PMID 26822779, 2016).
myocardial ischemia (4 papers, 2013 to 2023). A disorder of cardiac function caused by insufficient blood flow to the muscle tissue of the heart. "Myocardial ischemia reperfusion injury in male rats aggravated cardiac damage through androgen receptor." (PMID 26384003, 2015). "We applied flutamide, which is a known androgen-receptor blocker, and investigated whether blocking the androgen receptor might influence the protective effect of ginseng on the myocardial ischemia reperfusion injury in an in vivo rat heart model." (PMID 24282438, 2013). "Taken together, these observations indicate that AR and PGR are potential druggable targets for myocardial ischemia, while their pharmacological targeting can be complicated due to drug compounds’ activities towards other sex hormone receptors." (PMID 34404849, 2021).